TRPV1 (transient receptor potential cation channel subfamily V member 1)
Diseases named in the same sentence as TRPV1 in open-access papers (continued):
Sharing a sentence is not in itself a finding about the gene and the disease.
osteosarcoma (12 papers, 2017 to 2025). A usually aggressive malignant bone-forming mesenchymal neoplasm, predominantly affecting adolescents and young adults. "We provide here the first data on the functional expression of the TRPA1 and TRPV1 ion channels in osteosarcoma, suggesting novel diagnostic and/or therapeutic perspectives." (PMID 38612571, 2024). "A subcutaneous injection of squamous cell carcinoma (SCC-7), SCC-158 cells, or osteosarcoma NCTC 2472 cells in animals caused heat hyperalgesia and higher TRPV1 expression in DRG, which were reduced via the administration of capsazepine (CPZ)." (PMID 39940997, 2025). "Western blot analysis further confirmed that total Src protein levels remained unchanged following either form of stimulation, reinforcing the notion that TRPV1-mediated modulation of Src is specific to the osteosarcoma context." (PMID 41009392, 2025). "In our study we aim to characterize the expression and functionality of the TRPA1 and TRPV1 channels in human and mouse osteosarcoma tissues and in a mouse cell line." (PMID 38612571, 2024). "Both TRPA1/Trpa1 and TRPV1/Trpv1 were expressed similarly in human and mouse osteosarcoma tissues, while Trpa1 transcripts were more abundantly present in K7M2 cells." (PMID 38612571, 2024). "The TRPV1 agonist resiniferatoxin enhanced the antiproliferation effect of BTX in human osteosarcoma HOS cell lines by aggravating apoptosis." (PMID 34131404, 2021). "We investigated the effects of JWH-133 (CB2 agonist) and RTX (TRPV1 agonist) in six human Osteosarcoma cell lines: MG-63, U-2OS, MNNG/HOS, Saos-2, KHOS/NP, Hs888Lu, by Apoptosis and Migration-Assay." (PMID 28903355, 2017). "TRPV1 activation appears central to fine-tuning epigenetic regulation by modulating Src subcellular localization, thereby contributing to the phenotypic divergence observed between osteosarcoma subtypes." (PMID 41009392, 2025). "Our results show that both CB2 stimulation and TRPV1 activation, in different Osteosarcoma cell lines, can act on the same pathways to obtain the same effect, indicating the Endocannabinoid/Endovanilloid system as a new therapeutic target in Osteosarcoma." (PMID 28903355, 2017). "In certain contexts (e.g., osteosarcoma PDT), TRPV1 activation reduces oxygen consumption and HIF-1α accumulation, biasing toward ferroptosis—emphasizing that TRPV1 outputs depend on dose, duration, and metabolic state." (PMID 41303593, 2025). "Non-neuronal TRPV1 could have a role in various cell types, like in neutrophils, macrophages and osteosarcoma cells, and might be involved in tumorigenesis and related pain." (PMID 38791867, 2024).
type 2 diabetes (12 papers, 2015 to 2025). "Moreover, TRPV1 variants have been associated with a higher risk of type 2 diabetes or of functional dyspepsia." (PMID 28658281, 2017). "It was concluded that TRPV1 channels mediate coupling of myocardial blood flow to cardiac metabolism via NO-dependent and BK channel-dependent pathways that are corrupted in type II diabetes due to decreased myocardial TRPV1 protein expression and perhaps impaired TRPV1 pH sensitivity." (PMID 33613196, 2020). "This response was associated with less brain oedema formation, suggesting that mice lacking TRPV1 are protected from the brain damage, coma, and death associated with protein leakage into the brain tissue secondary to plasmodium infection." (PMID 31223430, 2019). "The vasorelaxant effects of CBD are reduced in patients with hypercholesterolemia and type-2 diabetes, which may be a result of a reduced TRPV1 component." (PMID 26092099, 2015). "The results show that the HTWP-acupuncture alleviation of the TBI-induced coma duration was offset by the i.c.v injection of P2RX7, P2RX3, and TRPV1 antagonists, indicating that P2RX7, P2RX3, and TRPV1 signaling pathways mediate the awakening effect of acupuncture at HTWP." (PMID 33519382, 2020). "Thus, we analyzed the distribution of P2RX7, P2RX3, and TRPV1 in the vPAG of sham and TBI rats without or with HTWP acupuncture treatment using confocal microscopy to verify that HTWP acupuncture regulates the expression of these receptors in the vPAG to reduce coma duration." (PMID 33519382, 2020).
ulcerative colitis (12 papers, 2014 to 2026). An inflammatory bowel disease involving the mucosal surface of the large intestine and rectum. "The expression of TRPV1 increases with age in the stomach and small intestine and is significantly decreased in patients with ulcerative colitis." (PMID 39338333, 2024). "Studies have also shown that CAP attenuates ulcerative colitis (UC) in mice by inhibiting the expression of oxidative stress proteins, proinflammatory cytokines, and TRPV1." (PMID 39199187, 2024). "The transient receptor potential vanilloid 1 (TRPV1) may play a role in the pathogenesis of ulcerative colitis (UC)." (PMID 30150894, 2018). "Patients suffering from ulcerative colitis and Crohn’s disease have shown upregulation in the expression of TRPA1 and TRPV1 mRNA, although results for TRPV1 are contradictory." (PMID 34912298, 2021). "Indeed, ulcerative colitis patients show a reduced expression of TRPV1, while during DSS-induced intestinal inflammation, no changes (acute inflammation) or increased expression (chronic inflammation) has been reported." (PMID 37893131, 2023). "The aim of this study was to evaluate the expression levels of TRPV1, TRPV2, TRPV3 and TRPV4 in mucosa epithelial cells of colonic biopsies from patients with ulcerative colitis (UC) in comparison to colonic resections from non-IBD patients (control group)." (PMID 29914124, 2018).
Cognitive impairment (11 papers, 2020 to 2026). Abnormal cognition is characterized by deficits in thinking, reasoning, or remembering. "The present study adds to this growing body of evidence by exploring the role of TRPV1 polymorphisms in cognitive impairment associated with PD." (PMID 41568154, 2026). "Concurrently, TRPV1 expression in the PBMCs of the patient group exhibited a strong correlation with those in the ADEs and was associated with the clinical symptoms and cognitive impairments of schizophrenia." (PMID 40309794, 2025). "With replication in larger and longitudinal cohorts, TRPV1 genotyping may eventually inform risk stratification or tailored interventions for cognitive impairment in PD." (PMID 41568154, 2026). "TRPV1 activation through chronic dietary capsaicin decreases amyloid pathology and attenuates cognitive deficits in APP/PS1 mice." (PMID 39468688, 2024). "We observed that TRPV1 activation by capsaicin effectively mitigates hippocampal tau accumulation‐induced synaptic damages, gliosis, and cognitive impairment in vivo." (PMID 37641913, 2024). "Jiang and colleagues have also reported that activation of TRPV1 can mitigate stress‐induced AD‐like neuropathological alterations and cognitive impairment in rats." (PMID 32061032, 2020). "Furthermore, the potential of TRPV1 as a therapeutic target for PD-related cognitive impairments merits further exploration." (PMID 41568154, 2026). "However, most studies on the role of TRPV1 channels in emotional and cognitive disorders are based on animal models, with limited clinical translational evidence available to date." (PMID 41459513, 2025). "The gut–brain–TRPV1 axis further illustrates how peripheral metabolic stressors and microbiome dysbiosis propagate to the brain via neuroimmune signaling, linking T1D to mood and cognitive disorders." (PMID 41463571, 2025). "Therefore, AS-IV may improve cognitive impairment by binding to AD-related gene, such as caspase-1, TRPV1, PSEN1, and GSK3Β, reduce cell death, and ultimately inhibit AD-phenotypes." (PMID 34616501, 2021). "The role of Trpv-1 and GPR-55 activation in reducing Aβ-induced impairments and cognitive deficits is established." (PMID 39201317, 2024). "Thus, regulation of TRPV1 may alleviate synaptic and cognitive impairments during AD development." (PMID 32061032, 2020). "Thus, both approaches targeting Trpv-1 and GPR-55 demonstrated significant reductions in neuronal degeneration and cognitive impairments, although through different molecular pathways." (PMID 39201317, 2024).
Cough (11 papers, 2006 to 2021). A sudden, audible expulsion of air from the lungs through a partially closed glottis, preceded by inhalation. "Capsazepine treatment inhibited virus induced up-regulation of TRPV1 indicating that these receptors are targets for treating virus-induced cough." (PMID 28187208, 2017). "The role of TRPV1-positive neurons in hypertussive cough was confirmed in rabbits chronically treated with capsaicin, resulting in a significant reduction in the cough response to citric acid following exposure to ozone." (PMID 26837703, 2016). "Our results show that inhalation of aerosolized TRPV1 or EP3 receptor antagonist sufficiently suppresses PGE2-evoked cough and that 24% vagal pulmonary C-neurons co-express TRPV1 and EP3 receptor with the cross-effect between TRPV1 and EP3 receptors in the neural excitability similarly to the cough." (PMID 33529249, 2021). "This provides a possible mechanism of how virus infection causes hypersensitisation in the airways and indicates that TRPV1, TRPA1 and ASIC3, or upstream events leading to their activation, are potential therapeutic targets for the treatment of virus-induced cough." (PMID 28187208, 2017). "The present study suggests that TRPV1 may play an important role in inflammatory cough." (PMID 17173683, 2006). "Indeed, TRPV-1-selective antagonists partially inhibit the tussive response to PGE2 and BK in a guinea pig cough model." (PMID 32938990, 2020). "SB705498, a potent selective TRPV1 antagonist, can exert significant antitussive effects and reduce neurogenic inflammation by reducing the expression of potent TRPV1 antagonism, demonstrating superior efficacy and potency in SP and CGRP in a capsaicin-induced cough model of guinea pigs." (PMID 31496955, 2019).
dermatitis (11 papers, 2016 to 2026). An inflammatory process affecting the skin. "Based on these data and our results, we hypothesize that the anti-dermatosis effects of HCRG21 are associated with an upregulation of the TRPV1-mediated IL-23/IL-17 signaling pathway." (PMID 41226679, 2025). "Despite the challenges of definitive demonstration of TRPV1 expression in rodent keratinocytes, multiple studies in rodents have suggested TRPV1 involvement in epidermal barrier function and the regulation of dermatitis." (PMID 27983625, 2016). "PAC-14028 is a potent TRPV1 inhibitor with an IC50 value of 55.0 ± 7.1 nM against capsaicin-induced calcium influx in rat DRG neurons, and it can attenuate dermatitis-associated barrier damages in Dermatophagoides farina- and oxazolone-induced mouse models of AD." (PMID 30301231, 2018). "Based on this, we might suggest that HCRG21 exhibits TRPV1-mediated anti-dermatosis effects." (PMID 41226679, 2025). "Compounds such as the TRPV1 blocker asivatrep and the TRPV3 inhibitor KM-001 have shown significant antipruritic effects in skin disorders, while tranilast, a TRPV2 antagonist, has provided concrete clinical evidence for TRP modulation in treating keloids." (PMID 41596464, 2026). "To further determine its selectivity, we tested the inhibition rate of fluoxetine on other dermatitis-related TRP channels transiently expressed in HEK293T cells, such as TRPV1, TRPV4, TRPA1, and TRPM8." (PMID 40699677, 2025). "Recently, CysLT receptor 2 expression was demonstrated to be present in approximately 40% of Trpv1+ neurons in mouse and human DRG where it contributed to itch in a model of dermatitis." (PMID 35503420, 2022). "Unexpectedly, TRPV1 but not TRPA1 protected against the SADBE-induced skin inflammation, suggesting that chronic skin inflammation and persistent itch in SADBE-induced CHS were mediated by distinct molecular mechanisms." (PMID 30301231, 2018). "The blockade of activation of TRPV1 by PAC-14028 is confirmed in murine AD models induced by Dermatophagoides farina (Df)- and oxazolone (OXZ), whose AD-like symptoms have been improved, including serum IgE increase, mast cell degranulation, scratching behavior, and clinical severity of dermatitis." (PMID 34276687, 2021). "In support of this hypothesis, we discovered that the absence of TRPV1+ nociceptors by genetic ablation reduced serum IgE levels 7.2-fold in mice with allergic airway inflammation and about 4.5-fold in mice with dermatitis." (PMID 34727095, 2021). "However, the apparent direction of TRPV1 effects on epidermal homeostasis and dermatitis has not been uniform across studies." (PMID 27983625, 2016). "Apart from TRPV1 and TRPA1, the levels of both IL-4 and IL-13, and epithelial-driven cytokines IL-25 and TSLP are also strongly correlated with expression of cold-activated TRPM8, a channel that is involved in non-neurogenic skin inflammation." (PMID 34276687, 2021).
gastric cancer (11 papers, 2020 to 2025). A primary or metastatic malignant neoplasm involving the stomach. "TRPV1 can inhibit the development of gastric cancer, and its downregulation is associated with poor survival in gastric cancer." (PMID 36304985, 2022). "The complete loss of TRPV1 in gastric carcinoma, as observed here, may imply a tumor suppressor role." (PMID 39125864, 2024). "A pending knowledge gap remains: it is unclear whether H. pylori-associated gastritis leads to TRPV1 overexpression, thereby increasing the risk of gastric cancer, or if the secondary epithelial changes associated with TRPV1 expression result in (pre)malignant transformation." (PMID 39125864, 2024). "Ionotropic receptors such as TRPM7 and TRPV1 are known to be involved in gastric cancer through the PLC/RAS/ERK pathway or through calcium loading via ERK/P38/JNK, activating cell proliferation or cell death." (PMID 40076652, 2025). "In the context of gastric cancer, dietary capsaicin promotes gastric cancer metastasis mediated through TRPV1." (PMID 39407657, 2024). "On the other hand, TRPV1 suppression correlates with reduced gastric cancer development through the calcineurin–NFAT pathway, which is crucial for T cell activation and immune response modulation against tumors." (PMID 39407657, 2024). "Mechanistic studies unravelled that the accelerated metastatic process induced by capsaicin was partially mediated by the upregulation of TRPV1 in the gastric cancer cells." (PMID 38129926, 2023). "It was demonstrated that high diet of capsaicin gave rise to accelerate tumor metastasis, which was partially mediated by elevating the expression of transient receptor potential vanilloid 1 (TRPV1) in gastric cancer cells." (PMID 38129926, 2023). "However, TRPV1 is downregulated in gastric cancer tissues, which affects cellular proliferation, migration, and invasion through the modulation of calcium signaling." (PMID 39407657, 2024). "Similarly, TRPV1 is closely associated with gastric cancer (GC); high TRPV1 expression indicates a good prognosis and is negatively correlated with tumor size, histological grade, and lymph node metastasis in GC." (PMID 38734935, 2024). "TRPV1 exceptionally suppresses the development of gastric cancer through a novel Ca2+/CaMKKβ/AMPK pathway, and its downregulation has been associated with poor survival in human gastric cancer patients." (PMID 37892239, 2023). "Collectively, our findings highlighted the potential risk of high capsaicin diet in promoting gastric cancer metastasis by virtue of modulating TRPV1 expression and gut microbiota composition, indicating the importance of controlled consumption of chili peppers for patients with gastric cancer." (PMID 38129926, 2023). "The main objective of this study was to evaluate TRPV1 expression in gastric cancer (GC) and precursor lesions compared with controls." (PMID 39125864, 2024). "Thus, our results demonstrate that the functional properties of the NANOG-TRPV1-pEGFR axis are conserved across NANOGhigh lung and gastric cancer cells, and TRPV1 could be a potential target for controlling NANOGhigh cisplatin-resistant cancer." (PMID 37165076, 2023). "Importantly, we found that genetic depletion of TRPV1 could reduce gastric cancer metastasis by diminishing the motility of tumor cells in vitro, but acted poorly in xenograft mouse model." (PMID 38129926, 2023). "Thus, TRPV1 upregulation and its downstream signaling may represent promising targets for gastric cancer prevention and therapy." (PMID 37892239, 2023). "TRPV-1 is overexpressed in a wide variety of cancers, and its expression correlates with poor prognosis; however, TRPV-1 activation suppresses development of gastric cancer." (PMID 40109334, 2025).
gastric cancer (continued). "It has also been demonstrated that this molecule promotes metastasis, particularly in lung and gastric cancers, due to its agonist activity on the Transient Receptor Potential Vanilloid-1 (TRPV1), a non-selective ligand-gated cation channel with high permeability to ionic calcium (Ca2+)." (PMID 40232070, 2025). "Although the aberrant expression and function of most Ca2+-permeable channels are known to promote gastrointestinal tumors, the association between transient receptor potential vanilloid receptor 1 (TRPV1) channels and gastric cancer (GC) has not yet been explored." (PMID 33008449, 2020).
metabolic syndrome (11 papers, 2016 to 2025). A cluster of metabolic risk factors for CARDIOVASCULAR DISEASES and TYPE 2 DIABETES MELLITUS. "This review surveyed the recent literature dealing with the role of TRPV1 in the hyperlipidemia-associated metabolic syndrome." (PMID 36589466, 2022). "Molecular mechanisms underlying lipid regulation are still unclear, however, TRPV1 has been suggested to be involved in the process, and despite considerable research efforts to understand the role of TRPV1 in the metabolic syndrome, the mechanism of action remains unresolved." (PMID 36589466, 2022). "Although studying the role of TRPV1 in lipid metabolism and TRPV1-lipid interaction are complex and demanding, so far it helped deepening the knowledge about TRPV1 functioning and offered promising approaches for treatment of metabolic syndrome associated with hyperlipidemia." (PMID 36589466, 2022). "Nicotinic acid, widely used for dyslipidemia, directly activates TRPV1, explaining flushing and revealing clinically relevant vascular effects." (PMID 41423466, 2025). "Taken together, these observations imply a complex, multifaceted and poorly understood role for TRPV1 in the pathogenesis of metabolic syndrome." (PMID 36551210, 2022). "There is a large body of experimental evidence linking the capsaicin receptor TRPV1 to metabolic syndrome." (PMID 36551210, 2022). "In the previous section, we discussed the studies which showed enhanced TRPV1 expression in metabolic syndrome." (PMID 36589466, 2022). "Expression of TRPV1 in various models of metabolic syndrome." (PMID 36589466, 2022). "In contrast, low expression of TRPV1 has been reported to be involved in metabolic syndrome." (PMID 36589466, 2022). "Therefore, a decrease in the expression of TRPV1 has been suggested to protect against metabolic syndrome." (PMID 36589466, 2022). "Furthermore, the identification of TRPV1 on metabolically-active tissues has also generated interest in the drug design and pharmaceutical industries for targeting TRPV1 to obtain capsaicin-like activity in attenuating metabolic syndrome." (PMID 29772784, 2018). "Therefore, one can argue that TRPV1 antagonists may also have a clinical value in preventing or mitigating the cardiovascular complications of metabolic syndrome." (PMID 36551210, 2022). "However, there are also many reports showing that TRPV1 activation can improve metabolic syndrome." (PMID 36424928, 2022). "Likewise, TRPV1 could effectively be targeted to treat metabolic syndrome." (PMID 32471282, 2020).